FOXA1 (forkhead box A1)
Diseases named in the same sentence as FOXA1 in open-access papers (continued):
Sharing a sentence is not in itself a finding about the gene and the disease.
cancer (continued). "Both INSR and FOXA1 were expressed at higher levels in OC cell lines than in FT190 cells, supporting a potential association with cancer." (PMID 39622796, 2024). "This underscores the broader potential of EP300/CREBBP inhibition in steroid receptor-driven cancers, with FOXA1 signaling occupying a central role in these effects." (PMID 38564048, 2024). "Previous studies have reported an interaction between AR and FOXA1 in cell proliferation related to human cancer." (PMID 38397387, 2024). "FOXA1 binds to ER and promotes the transcription program of drug-resistance-related genes, which favors cancer progression and drug resistance." (PMID 38605023, 2024). "Analysis of ChIP-seq peaks revealed that over 30% of REV-ERBα peaks overlapped with FOXA1 peaks in different cancer cells." (PMID 39383000, 2024). "Since both FOXA1 and GR possess a role beyond PCa, we extended the examination of the two TFs to other cancers." (PMID 38015476, 2024). "In particular, known cancer-related transcription factors such as FOXA1 act as modulators of DNA methylation at binding sites." (PMID 38566132, 2024). "A total of 136 nonsilent NSMs were identified in normal samples, with an average of 4.9, and 81 NSMs were identified in BPHs, with an average of 6.3, in the trio cases (p = 0.042), including the COSMIC cancer genes FOXA1, KMT2C, and BCOR." (PMID 38172600, 2024). "Nevertheless, the association between Hypo-MS4 and neoantigen load as well as the suppression of immune responses in the TIME further strengthened the relationship between FOXA1 activity and cancer immunity." (PMID 38566132, 2024). "FOXA1 mutation induces AR reprogramming and transforming growth factor beta (TGF-β) pathway activation to promote EMT-driven cancer metastasis compared with wild type." (PMID 38605023, 2024). "For example, myelocytomatosis (MYC) is a notorious oncoprotein overexpressed in most of human cancers, and androgen receptor (AR) and forkhead box A1 (FOXA1) are pioneer factors in PRAD." (PMID 39436262, 2024). "The results showed that FOXA1 expression in the cancer tissues was weaker than that in the adjacent tissues of GBC clinical specimens." (PMID 38886389, 2024). "GATA3-/FOXA1- was associated with shorter Disease-Free Survival (DFS) (P=0.001) and Cancer-Specific Survival (CSS) (P<0.001) than other combination groups." (PMID 38425344, 2024). "Comparison of the role of mutant and wild-type FOXA1 in PCa growth showed that patients with FOXA1-mutated PCa had a poorer prognosis; furthermore, almost all FOXA1 mutants resulted in increased cancer cell growth compared with FOXA1 overexpression." (PMID 38605023, 2024). "Together, these results suggest that REV-ERBα cooperates closely with FOXA1 in directly stimulating the expression of the tumorigenic programs in cancer cells." (PMID 39383000, 2024). "Semaphorin 3C (SEMA3C) is a secreted autocrine growth factor that drives growth and treatment resistance of prostate and other cancers and is known to be regulated by both AR and FOXA1." (PMID 38528115, 2024). "Among the 33 cancer types, 26 types of analysis showed that the mRNA expression level of FOXA1 was significantly different between cancer tissue and precancerous tissue, among which 19 types showed upregulated expression and 7 types downregulated expression." (PMID 38608123, 2024). "FOXA1 is a pioneer of epigenetic reprogramming in both stem cells and cancer cells and is involved in DNA repair complex formation and DNA demethylation." (PMID 38566132, 2024).
cancer (continued). "In particular, we demonstrated how cancer-related transcription factors, such as FOXA1, act as modulators of DNA methylation at specific loci and thereby reprogram the cancer epigenome to alter relevant biological functions." (PMID 38566132, 2024). "We next focused on the targets of 10 key FOX genes (FOXA1, etc.)in 9 cancers with notable alterations in either cancer genome or transcriptome to gain insight into the function role of FOX targets." (PMID 37401400, 2023). "We also note that transcription factor motif enrichment analysis of the cancer-specific enhancers revealed FOXA1, MESP1/2, and TFAP2C as the top three transcription factors enriched at these enhancers based on adjusted p-value." (PMID 37685859, 2023). "FOXA1 is a crucial transcription factor functionally involved in the initiation and development of many types of cancers, including PCa." (PMID 36998469, 2023). "For example, FOXA1 overexpression can suppress the cancer immune response and promote cancer immuno- and chemotherapy resistance." (PMID 36622275, 2023). "Further mechanisms have been proposed to explain the role of FOXA1 during progression in different cancer models." (PMID 36230619, 2022). "Other members of the FOX family of TFs such as FOXA1, FOXM1, and FOXP1 are considered oncogenes and FOXC1 was implicated in cancer stemness through modulation of β-catenin signaling." (PMID 35349489, 2022). "LncRNA can form a positive feedback loop with YBX1 to activate the FOXA1 transcription network in cancer." (PMID 36169095, 2022). "scATAC and CUT&Tag experiments revealed two distal regulatory regions (L1 and L4) specifically bound by FOXA1 and opened in the basal cancer cell types (basal and TPCS)." (PMID 35968916, 2022). "Of these, we established a role for the FOXA1-enhanced PTC-preventing exon 30 in the cancer gene FLNA as a promoter of PC cell growth." (PMID 36170835, 2022). "ZFP91 takes part in different biological processes, and it promotes cancer development by the control of the NF-кB signaling pathway, FOXA1, HIF-1α, and so on 29,31,44." (PMID 35165513, 2022). "FOXA1 marks genomic signatures in a cell-specific manner and regulates gene expression differentially in different human cancer cell lines." (PMID 35879772, 2022). "Worthy of note, FOXA1 mRNA and protein levels are also closely related with those of AR in hormone-dependent cancer models." (PMID 36230619, 2022). "FOXA1 functions as an oncogenic pioneering and transcription factor in cancers, including prostate and breast." (PMID 35550030, 2022). "For the analysis, we used next-generation sequencing with the Hot Spot Cancer Panel provided by Illumina Inc., San Diego, CA, USA, and an immunohistochemical analysis of FOXA1, FOXP1, and estrogen receptors." (PMID 36012038, 2022). "Clearly the systems-wide impact on AS mediated by FOXA1 is likely to have a profound effect on cancer severity." (PMID 36170835, 2022). "For example, the lncRNA DSCAM-AS1 undergoes interaction with Y box binding protein 1 (YBX1), thereby promoting cancer growth by activating the forkhead box A1 (FOXA1) transcription network in a positive feedback loop." (PMID 35412951, 2022). "Last we tested the consequence of TF binding on DNA methylation patterns by deleting FOXA1 or GATA3 in HCC1954 cancer cells." (PMID 35331302, 2022). "For example, FOXA1 (HNF3A) is a TF involved in embryonic development which plays an important role in cancer." (PMID 34986601, 2022). "To assess the prognostic value of FOXA1, we performed the Kaplan-Meier survival analysis in pan-cancer." (PMID 36393971, 2022). "This is mirrored by expression analysis – FOXA1 is high in cancer cells but has low expression in fibroblasts, while the proteins of AP-1 complex are more highly expressed in fibroblasts." (PMID 37435460, 2022). "Some bioinformation analysis of data download from cancer databases regarding FOXA1 and HDAC3 expression should be added in the further analysis." (PMID 34991620, 2022).
cancer (continued). "The overexpression of FOXA1 was also reported in several cancer types, and thus, it serves as a significant indicator of the poor overall survival (OS) of patients." (PMID 36393971, 2022). "FOXA1 and FOXA2 TFs contribute to the maintenance of epithelial cell identity and their deregulated expression is associated with cancer formation." (PMID 36509813, 2022). "Pan-cancer analyses were performed to explore the features of forkhead-box (FOX) A1 (FOXA1) using data from TCGA and GTEx databases." (PMID 36393971, 2022). "High expression of FOXA1 was mainly related to extracellular matrix organization, cancer, and the M phase, among other pathways." (PMID 35968505, 2022). "These investigations provide the first evidence of a transcriptional pathway linking JAM-A, HER2 and FOXA1 in cancer settings, and support potential future pharmacological targeting of JAM-A as an upstream regulator of HER2." (PMID 35203384, 2022). "Studies have shown that FOXA1 is expressed in a variety of cancers, but its role varies in different tumors." (PMID 35968505, 2022). "Collectively, these data highlight important functional impacts of a possible JAM-A, HER2 and FOXA1 axis on cancer patient outcomes." (PMID 35203384, 2022). "Luminal cancer cells are controlled by the transcriptional master regulators, such as FOXA1, PPARγ, and GATA3." (PMID 34831307, 2021). "The genomic region inculpating the FOXA1 gene is amplified in different cancers with the prior evidence collected from prostate and BC." (PMID 36046086, 2021). "Cell lines dependent on FOXA1 were derived from multiple types of cancer cells, including breast, large intestine, liver, lung, stomach, and urinary tract suggesting that FOXA1 is a more conserved dependency." (PMID 33842927, 2021). "The transcription factor FOXA1 has been proven to regulate transcriptional programs in both normal prostate tissue and cancer tissues by directly interacting with AR." (PMID 34445492, 2021). "SAHA does not affect the nuclear translocation and expression of Twist, Snail, Slug, and ZEB EMT-related transcription factors; however, it affected forkhead box protein A1 (FOXA1) expression, a leading cancer progression factor, in MCF7 and T47D BC cells." (PMID 34572928, 2021). "In contrast, A549 cancer-specific enhancers contained considerably fewer instances of FOXA1 and NKX2–1 peak co-occurrence (8.6%)." (PMID 34922464, 2021). "We also checked the patient outcome data using the Cistrome cancer database for TF profiles of FOXA1, HOXB13 and CDX2 in the TCGA PRAD data set54,55." (PMID 34911933, 2021). "Several known cancer-associated genes are located on 14q, including CHD8, FOXA1, HIF1A, and DICER1, encoding proteins involved in DNA damage/response, hypoxia response, and miRNA processing, respectively." (PMID 34205964, 2021). "FOXO genes are rearranged in various cancers; FOXA1 is mutated in prostate and breast tumors, while FOXM1 has been shown to be a potent outcome predictor in various cancer types." (PMID 32214027, 2020). "For example, in ‘Search accessible regions by TF’, we input ‘FOXA1’ in ‘Motif’, ‘Cancer Type’ in ‘PRAD’ and started." (PMID 35134148, 2020). "Pioneer factors like FOXA1 not only drive tumorigenesis but also participate in maintaining the malignant characteristic of tumors, thus making FOXA1 a potential therapeutic target for cancers." (PMID 32929382, 2020). "siRNA also indicated that the relationship between FOXA1 and IGFBP-2 in cancer cells was different, as although silencing FOXA1 reduced levels of IGFBP-2, the ratio of FOXA1 to IGFBP-2 appeared to remain the same." (PMID 32655839, 2020). "Our study revealed that the lineage-specific expression of DSCAM-AS1 was regulated by the FOXA1-driven super-enhancers (SEs) and DSCAM-AS1 can regulate expression of FOXA1 and ERα to maintain the characteristics of indicated cancer cells." (PMID 32929382, 2020).
cancer (continued). "FOXA1 is an activated oncogenic transcription factor and acts as a crucial oncogene in the development of a variety of cancers like PRAD, BRCA, and LUAD by modulating a number of protein-coding genes that are involved in various cellular processes." (PMID 32929382, 2020). "Functionally, FOXA1 is a member of the transcription family and a very well-characterised biomarker for triple-negatives and other carcinomas." (PMID 32182819, 2020). "Our present study also showed a tendency for a better prognosis in cancers with FOXA1 or GATA3 expression." (PMID 31500577, 2019). "FOXA1, a member of the forkhead transcription factor family, is closely related to the formation and progression of many human cancers, including OS." (PMID 31801112, 2019). "Forkhead Box A1, also known as hepatocyte nuclear factor 3α, is a transcription factor that plays important roles in development as well as cancer formation." (PMID 31598425, 2019). "Seventy-eight (43%) of the carcinomas contained at least one FOXA1-positive neoplastic cell whereas the other 102 (57%) were completely devoid of FOXA1 expression." (PMID 31888566, 2019). "Analysis of RNA sequencing data from 33 cancer types revealed that AL121790.1 expression is strongly correlated with FOXA1 expression (Spearman correlation = 0.84)." (PMID 30272002, 2018). "rs5414555835 (also annotated with ID rs67668514) maps to a locus bound by FOXA1 in various cancer cell lines and displays active histone marks in liver and brain cells." (PMID 29669022, 2018). "Some studies suggested that FOXA1 was potentially an oncogene because overexpression or increased copy numbers of FOXA1 were found in a variety of cancers." (PMID 29883365, 2018). "Some studies demonstrated that forkhead box protein A1 (FOXA1), a member of forkhead box gene superfamily, inhibits apoptosis in cancer cells." (PMID 30486435, 2018). "Taken together, we have shown that the FOXA1/JUND /FOSL2-TXNDC9-MYC regulatory network promoted cancer progression of HCC." (PMID 30382079, 2018). "Segmental expansion of the FoxA1+ LOP cell population occurs with advanced age and confers an increased risk of this ER+ phenotype cancer." (PMID 28865492, 2017). "The mean FOXA1 mRNA values were 11.40 (SD = 0.92) in ER-positive cancers and 8.72 (SD = 2.32) in ER-negative cancers." (PMID 29137314, 2017). "The variation of G7193T was predicted at the binding site for the cellular transcription factor FOXA1, which has been reported as a pioneer transcription factor that regulates the progression of cancer in the breast, liver, prostate, lung, and endometrium." (PMID 28767682, 2017). "The identification of FOXA1 or FOXA2 as essential transcription factors in cancer cells proposes the existence of a conserved role of the FOXA family in the core transcriptional regulatory circuitry." (PMID 27739523, 2016). "Most of the basal miRNAs targeted factors that have been implicated in the control of luminal biology (FOXA1, ERBB2), adipogenesis (FGFR2, FGFR3) and urothelial differentiation (HOX5/8/13), all of which would be predicted to be suppressed in basal cancers." (PMID 27845906, 2016). "Specifically expressed in myoepithelial cells and breast basal-like carcinomas, SOX9 and SOX10 have proven to be negatively associated with FOXA1, which encodes FoxA1 transcription factor, an essential regulator of mammary ductal morphogenesis." (PMID 25962646, 2015). "Increasing evidence suggests that forkhead box A1 (FOXA1) is frequently dysregulated in many types of human cancers." (PMID 24512546, 2014). "The role of FOXA1 as a pioneer factor for ERα has also been found to differ in various cancer cell types." (PMID 24849812, 2014).
cancer (continued). "The present special Research Topic of Frontiers in Oncology is devoted to unveiling this new information, focusing on the role and regulation of FoxA1, FoxO3a, and FoxM1 in cancer initiation, progression, and drug resistance." (PMID 25401090, 2014). "More comprehensive studies covering several EC cell lines in different cancer subtypes will be necessary to define the role of FOXA1 in EC development." (PMID 24512546, 2014). "We propose this is a determinant of the papillary genotype of these cancers and that FOXA1 is a key mediator of this evolution." (PMID 25071007, 2014). "When compared, genes with upregulation in FGFR3 mutant cancers had significantly higher expression in the FOXA1 transfected cells (average 1.10±0.2 fold change, p<0.001) than those without change." (PMID 25071007, 2014). "In breast hormone-sensitive and resistant cancer cell lines, almost all ER–chromatin interactions and gene expression changes are dependent on the expression of FOXA1." (PMID 23192763, 2013). "This is a novel function of Foxa1, which has implications for the role of Foxa1 in cell cycle progression and cancer." (PMID 22737085, 2012). "The function of Foxa1 has been studied primarily in a variety of cancer cell lines and, together with Foxa2, during embryonic development." (PMID 22737085, 2012). "A strong FOXA1 immunoreaction was detected in the nuclei of cells in the cancer lesion, whereas cells in the NAT showed weak immunostaining mainly at the cytoplasm." (PMID 22879989, 2012). "‘Cyclin-dependent kinase activity’ and ‘cancer’ are among the top biological pathway enriched among the Foxa1-only gene targets." (PMID 22737085, 2012). "In a recent study, it was found that FOXA1 is expressed predominantly in luminal type A carcinomas, making it a potential marker of good prognosis." (PMID 21079769, 2010). "In our cohort of patients with PCa, AR, FOXA1, MTOR, and MDM2 showed the highest rate of novel and pathogenic mutations, with 7, 3, 3, and 2, respectively, evidencing their relevance in this type of cancer." (PMID 41009328, 2025). "We also identified motifs for several transcription factors (TFs) in MYB-binding DNA sequences, including AP1, KLF5, ETS1, FOXA1 and other cancer-related TFs, suggesting that these TFs may work together with MYB in transcriptional regulation." (PMID 40234694, 2025). "And YBX1 could interact with lncRNA DSCAM-AS1 to disrupt the role of SE in inactivating the FOXA1 transcription network in cancer." (PMID 40790233, 2025). "To investigate whether phosphorylated FOXA1 functions as a cancer-promoting protein, we constructed PCa cell lines stably expressing FOXA1 WT, S234A, or S234E and performed a series of functional experiments." (PMID 41395253, 2025). "Our results indicate that the NR3C1 repression by FOXA1 might be a prominent mechanism to restrict the GR action in cancers." (PMID 38015476, 2024). "Furthermore, the article describes the prospect of targeting upstream regulators of FOXA1/FOXA2 to regulate its expression for cancer therapy because of the drug untargetability of FOXA1/FOXA2." (PMID 38605023, 2024). "Although many cell and animal experiments have demonstrated that FOXA1/FOXA2 knockout can significantly inhibit cancer progression, FOXAs themselves are undruggable targets for clinical application because of their intricate transcriptional network as transcription factors." (PMID 38605023, 2024). "To investigate if FOXA1 might also affect the HR+ cancer cell movement and metastasis, we studied its effect through wound healing and the Boyden chamber assays." (PMID 39000600, 2024). "Indeed, an examination of gene expression profiles from multiple datasets of PCa patients revealed a significant reduction in FOXA1 transcript levels as the cancer progresses from its primary state to CRPC." (PMID 38015476, 2024).